CTNNB1 (catenin beta 1)
Diseases named in the same sentence as CTNNB1 in open-access papers (continued):
Sharing a sentence is not in itself a finding about the gene and the disease.
tumor (continued). "The recent next-generation sequencing data suggest that the integration of the viral genome in the non-tumor tissue is dispersed throughout the genome with no hotspot while tumor tissue showed enrichment of particular genomic sites such as MLL4, TERT, and CTNNB1." (PMID 34526974, 2021). "Interestingly, viability of HAP1 cells did not seem to be affected by the knockout of known tumor type-specific oncogenes such as BCR, PIK3CA, KRAS, CTNNB1, or BRAF." (PMID 33228647, 2020). "No expression of CTNNB1, CTLA4, EPCAM, ERBB2, MET, p40, PD-L1 and SOX2 could be detected in any of the tumors, PD-L1 was negative in tumor as well as stromal cells." (PMID 26943575, 2016). "In BCPAP cells treated for 72 h, genes from the canonical Wnt pathway (FZD1, DVL1, AKT2, CTNNB1, LEF1, MYC) and the non-canonical Wnt pathway (RHOA, related to cytoskeletal dynamics and increased migration and invasion) were upregulated, suggesting pro-tumor behavior." (PMID 39125748, 2024).
cancer (767 papers, 2007 to 2026). A tumor composed of atypical neoplastic, often pleomorphic cells that invade other tissues. "Genes such as PIK3CA, FAT1, FAT4, and CTNNB1 exhibit relatively similar mutation frequencies across both cancers, though slightly higher in SC for PIK3CA and FAT1/FAT4." (PMID 41419500, 2025). "Mutations in the CTNNB1 gene activate the Wnt/β-catenin signaling pathway, which promotes cancer cell growth and inhibits apoptosis." (PMID 40869967, 2025). "Similar to the patients with Cowden/Cowden-like syndrome, Ambra1 cKO mice were susceptible to malignant tumors, some of which contained hotspot mutations in Kras (G12D) and Ctnnb1 (G34E)." (PMID 40734673, 2025). "Mutations in catenin beta 1 (CTNNB1) in cancer lead to increased stability of the β-catenin protein and sustained activation of the WNT/β-catenin signaling pathway." (PMID 40032852, 2025). "Mutations in CTNNB1, which encodes β-catenin, have increasingly been recognized as significant drivers of various cancers, including PDEECs." (PMID 40072110, 2025). "ZNRF3-mutant CRCs carrying additional APC truncations or oncogenic CTNNB1 mutations classically linked to β-catenin activation, are only observed in 5 and 1 cancer, respectively." (PMID 39674817, 2025). "Somatic missense variants of the CTNNB1 gene in cancer patients also merit further investigation, as somatic GoF variants are functionally different from therapeutic overexpression, such as gene replacement." (PMID 40684264, 2025). "Mutations in CTNNB1 lead to the abnormal stabilization and accumulation of β-catenin, triggering the activation of Wnt signaling and the development of various cancers." (PMID 40180907, 2025). "CTNNB1 is an effector of the WNT signaling pathway which has been reported to be mutated in various cancers, including ETMR." (PMID 40680886, 2025). "Specifically, we found that CTNNB1 mutated carcinomas showed significantly downregulated levels of ITGAL, ITGAM, and ITGB2, which are involved in leukocyte transendothelial migration." (PMID 41227323, 2025). "Recent molecular analyses have demonstrated that in mixed tumors, the YST and carcinoma components can harbor shared somatic mutations, including CTNNB1 and ARID1A, implying a common clonal origin and supporting the theory of somatic derivation." (PMID 41510478, 2025). "Our results suggest that immunotherapy approaches aimed at low-grade early-stage carcinomas should consider CTNNB1 mutation status when developing treatment strategies." (PMID 41227323, 2025). "In recent years, mutations in CTNNB1 have been associated with worse prognosis in low-risk carcinomas." (PMID 41227323, 2025). "Previous studies have shown that MEK inhibitors reduce cell proliferation but increase the expression of genes such as Ctnnb1, Axin2, and Lgr5, which are highly associated with cancer development." (PMID 38277448, 2024). "We further uncovered a cancer-associated S33F CTNNB1 mutation which generates a novel binding site for G3BP1/2 (p + 3 position of the [FILV]xFG-motif)." (PMID 39009827, 2024). "Exon 3 mutations in the CTNNB1 gene, responsible for encoding the β-catenin protein, have been identified in association with several cancers." (PMID 39734333, 2024). "The analysis detected many genetic variants and mutations in genes related to cancer, including CTNNB1 and WT1, which have been previously reported to be associated with WT." (PMID 38672648, 2024). "Genetic alterations in LNMs are associated with the loss of adhesion molecules such as CTNNB1, emphasizing the clinical impact of LNMs in cancer trajectory." (PMID 39329741, 2024). "MiR-184 was the next most downregulated miRNA in cancers with CTNNB1 mutations, with a fold change of 0.56." (PMID 37958433, 2023).
cancer (continued). "This suggests that cancer cells harbouring mutations in components of the destruction complex or CTNNB1 would likely be insensitive to OMP-18R5 treatment." (PMID 37048063, 2023). "While these tumors tend to be early stage with lower rates of myometrial and lymphovascular invasion, CTNNB1-mutated cancers show increased rates of recurrence." (PMID 37958433, 2023). "Loss of CDH1 (E-cadherin) and CTNNB1 expressions resulted in increased cell motility and advanced cancer stages and are associated with EMT, a key event during EC development." (PMID 37313172, 2023). "CTNNB1 is part of the Wnt/β-catenin pathway, which is commonly known to have mutations in various cancers in which it leads to advanced disease and is difficult to target." (PMID 37370820, 2023). "Accumulated studies have demonstrated that the activation of β-catenin (CTNNB1) is associated with angiogenesis and cancer metastasis by modulating the expression of VEGF and the matrix metalloproteinases (MMPs) pathway in CRC." (PMID 36672201, 2023). "We found few shared genetic events between these close lesions: the intramucosal carcinoma and high-grade dysplasia analyzed from mouse 2609 shared a CTNNB1 mutation and the two intramucosal carcinomas from mouse 3608 harbored no shared alterations." (PMID 36611031, 2023). "Catenin Beta 1 (CTNNB1) mutations are typically found in low-grade carcinomas with endometrioid histology." (PMID 37958433, 2023). "Alterations to Wnt-signaling proteins and mutations in CTNNB1 are associated with multiple types of cancer." (PMID 36248967, 2022). "By simulating somatic mutation of CTNNB1 in patients, we nevertheless demonstrate that activated β-catenin causes both benign and malignant tumors in mice." (PMID 36122209, 2022). "Although mutation of CTNNB1 was shown to be associated with HBV-related cancer in previous research, other functional mechanisms of CTNNB1 in HBV-related HCC have also gradually been revealed." (PMID 35356220, 2022). "Based on a published catalog of statistically significant hotspot mutations in cancer, however, nearly all missense CTNNB1 mutations in this cohort were in hotspots." (PMID 34986841, 2022). "Previous studies have found CTNNB1 mutations in association with several types of cancer, with a hot spot region targeting the exon three (encoding residues 5–80 from β-catenin)." (PMID 35053583, 2022). "Through the IPA search, CTNNA1 and CTNNB1 were related to cancer, among which CTNNB1 was a diagnostic marker for many kinds of cancer." (PMID 35268705, 2022). "BRAF and CTNNB1, two oncogenes frequently mutated in childhood cancers, showed higher mutation rates in AYAs." (PMID 36433963, 2022). "In HPV-induced cancers, mutations in the Catenin Beta 1 (CTNNB1) and AXIN1 genes, components of the Wnt pathway, are uncommon." (PMID 37305016, 2022). "The researchers had also linked CTNNB1 gene variants to susceptibility and prognosis of some cancers." (PMID 36569862, 2022). "GOF CTNNB1 mutations, especially point mutations, are attractive targets for such a gene editing approach for cancer treatment." (PMID 35166233, 2022). "Canonical CTNNB1 p.Ser45Pro missense mutation, as well as several other cancer-related genes (e.g., PML, HSP90AA1, BAZ1A, ARHGAP5, LHFPL6), were detected in the PT sample." (PMID 35860547, 2022). "Because exon 3 is the most common locus of CTNNB1 mutation in cancer, exon 3–deleted mice are widely used for the study of β-catenin activation." (PMID 36122209, 2022). "CTNNB1 was recently reported to be mutated in PTCa, and to ultimately promote cancer development and stemness." (PMID 35205190, 2022).
cancer (continued). "Aberrant β-catenin immunostaining in cancer cells was observed in 9 out of 22 cases, of which 3 cases had the CTNNB1 mutation, one case had the APC mutation, and the remaining 5 cases had no mutations with Wnt pathway associated genes." (PMID 35778698, 2022). "Ctnnb1 encodes β-catenin, which is well known to play a role in cancer, and this gene is mutated in other carcinogen as well as spontaneous murine tumors." (PMID 35482806, 2022). "Both gain-of-function and loss-of-function CTNNB1 mutations are found in multiple human cancer types." (PMID 36499305, 2022). "Further, mutations in CTNNB1 are associated with worsened survival in patients with low grade, endometrioid type cancers." (PMID 36248967, 2022). "CTNNB1 mutation frequency in incident cancers is particularly low when restricting the comparison to MLH1-associated LS cancers." (PMID 34206061, 2021). "β-catenin, a protein involved in signal transduction of the Wnt signaling pathway, encoded by the CTNNB1 gene, is frequently altered in cancer." (PMID 34205480, 2021). "We also preliminarily verified the function of cancer-associated candidate genes (CTNNB1 and KMT2D)." (PMID 33968779, 2021). "Somatic mutations in CTNNB1 were reported to stabilize β-catenin protein that translocate to the nucleus to activate Wnt signaling pathway in several cancers." (PMID 34922552, 2021). "Somatic mutations in the CTNNB1 gene have been identified in several types of cancer including include colorectal, liver, thyroid, ovarian, endometrial and skin cancers and medulloblastoma." (PMID 33237662, 2021). "Since the mutation rate of CTNNB1 gene is relatively higher in HCC than in other types of cancer, clinical trials of ICIs should be conducted or subanalyzed for HCC with wild-type and mutated β-catenin separately." (PMID 34429454, 2021). "Approximately 300 co-clustering phosphosites are verified in patient samples of 5 cancer types or previously implicated in cancer, including CTNNB1 p.S29/Y30, EGFR p.S720, MAPK1 p.S142, and PTPN12 p.S275." (PMID 33875650, 2021). "Taken together, these studies show that activation of the PD-1/PD-L1 pathway during HCC has a good prognosis and that the CTNNB1 mutation suppresses cancer immunity." (PMID 34071550, 2021). "WNT signaling is often disrupted in cancer, frequently due to inactivating mutations in negative regulators or due to activating mutations in CTNNB1 itself." (PMID 34190040, 2021). "Other genes participating in this pathway frequently mutated in cancer include AXIN2/Axin2 (LOF) as well as CTNNB1/Ctnnb1 gain-of-function (GOF), the last encoding for the β-catenin protein." (PMID 34956074, 2021). "We observed from the expression correlation heatmap that CTNNB1 was significantly associated with lncRNA KCNQ1OT1 across cancers." (PMID 33994860, 2021). "We found a rather narrow range of other genes (KMT2D, FBXW7, GNAS, ARID1A, NF1 and CTNNB1) harbouring mutations in 6–12% of the patients and a long tail of cancer genes with mutations in <6%." (PMID 34647903, 2021). "Tumors with mutations in this pathway, particularly in CTNNB1, have low levels of immune cells across multiple cancer types, likely through the exclusion of BATF3‐derived dendritic cells from the TME." (PMID 32239503, 2020). "In both studies, codons 41 and 45 of CTNNB1 were found as mutational hotspots in MSI-H cancers while in MSS cancers larger deletions including the β-TRcP binding site dominated." (PMID 33115416, 2020). "In cancers, mutations in CTNNB1 are often found in the hotspot region encoding for codons D32 to S452,29,30." (PMID 32686686, 2020).
cancer (continued). "In most cancers, mutations are found in exon 3 of the CTNNB1 gene and its presence has been associated with an aggressive phenotype in several types of tumors, such as endometrial, hepatocellular, and thyroid cancers." (PMID 32651460, 2020). "In recent years, several studies have suggested the significant association between the CTNNB1: rs1880481 and cancer prognosis." (PMID 32453708, 2020). "Examination of the ultra‐deep sequencing panel data from the analyzed regions revealed six mutations in cancer genes in all samples and one heterogeneous mutation (CTNNB1 P492S) confined to PT3, PT5, and IT4." (PMID 31811783, 2020). "Homo- or hemizygous CTNNB1 mutations were detected in 74% of CTNNB1 mutated CRCs (13 microsatellite instabile (MSI-H), 7 microsatellite stabile (MSS)) but only in 3% (1/33) of extracolonic CTNNB1 mutated cancers." (PMID 33115416, 2020). "Genetic changes in components of WNT/β-catenin signaling such as deletion of the APC gene and CTNNB1 mutations have been frequently detected in many types of human cancers." (PMID 32838807, 2020). "It is well known that inhibition of E-Cadherin will cause an accumulation of CTNNB1 within cells leading to nuclear translocation where the abnormal accumulation of CTNNB1 is significantly associated with many cancers." (PMID 34466597, 2020). "Mutations are mostly detected in genes encoding components of the destruction complex such as APC and AXIN, but the gene encoding β-catenin, CTNNB1, is also frequently mutated in selected cancer types." (PMID 32659938, 2020). "Among the 160 cancer-related genes examined, the analysis revealed only a missense mutation in the CTNNB1 gene (c.110C > G, p.S37C)." (PMID 30206803, 2019). "For example, CTNNB1, an oncogene of many cancers, was found to be associated with endogenous stimulation, epigenetic control and ovulation." (PMID 31205821, 2019). "Gain-of-function mutations in CTNNB1 are detected in numerous human cancers; therefore, it is necessary to explore the role of Wnt/β-catenin regulated genes in BLCA." (PMID 31766561, 2019). "APC, which is mutated in several cancers, is a well-established negative regulator of CTNNB1 (β-catenin) and WNT signaling." (PMID 30224629, 2018). "In the current study, we identified Nutlin‐3a, a classic MDM2 inhibitor, with unexpected drug effect in CTNNB1‐mutated cancer cells." (PMID 29532999, 2018). "Only one compound, Nutlin‐3a, an MDM2 inhibitor, was significantly sensitive in 18 cancer cells with CTNNB1 mutation." (PMID 29532999, 2018). "Our first goal is to briefly portray a picture of genetic alterations associated with PI3K/AKT, Wnt-CTNNB1, andNF-κB signaling pathways and their role in the initiation and progression of cancer." (PMID 29094602, 2018). "Herein we review the current understanding of CTNNB1 mutations, their roles in tumorigenesis and discuss their possible therapeutic implications for cancer." (PMID 29435196, 2018). "In our study, we aim to explore the online Genomics of Drug Sensitivity in Cancer (GDSC) database to screen drug sensitivity in cells with CTNNB1 mutation." (PMID 29532999, 2018). "In summary, we systematically reviewed the relationship between CTNNB1 polymorphisms and overall cancer risk." (PMID 28963373, 2017). "In the present study, we systematically reviewed the relationship between CTNNB1 SNPs and overall cancer risk." (PMID 28963373, 2017). "We examined CDH1 and CTNNB1 mutations in a wide variety of anatomic sites that collectively account for most cancer cases." (PMID 29156750, 2017).